SLC35F1 (solute carrier family 35 member F1)
Description:
Putative solute transporter.
Synonyms: C6orf169; dJ230I3.1
Tractability: Antibody: UniProt predicts a signal peptide or a membrane-spanning region. PROTAC: its protein half-life has been measured.
Gene: Protein-coding gene on chromosome 6 (117,907,264 to 118,317,676, forward strand). Ensembl gene ENSG00000196376.
Subcellular location: Cytoplasmic vesicle, secretory vesicle, synaptic vesicle membrane
Subcellular location (Human Protein Atlas): Nucleoplasm; Centriolar satellite; Cytosol
Gene Ontology:
Molecular function: protein binding; transmembrane transporter activity
Biological process: transmembrane transport
Cellular component: synaptic vesicle membrane; membrane
Genetic constraint (gnomAD): Loss-of-function variants: 14 observed, 46.12 expected, observed/expected ratio (o/e) 0.3, 90% interval 0.2 to 0.47. The upper end of that interval is the gene's LOEUF score, 0.47, which puts it in group 2 of 6, group 1 being the genes least tolerant of losing a copy. Missense variants: 392 observed, 487.02 expected, observed/expected ratio (o/e) 0.8, 90% interval 0.74 to 0.88. Synonymous variants: 183 observed, 191 expected, observed/expected ratio (o/e) 0.96, 90% interval 0.85 to 1.08.
Homologues: Orthologues: chimpanzee SLC35F1 (100% identical), macaque SLC35F1 (99% identical), rabbit SLC35F1 (99% identical), dog SLC35F1 (97% identical), mouse Slc35f1 (97% identical), rat Slc35f1 (96% identical), pig SLC35F1 (84% identical), guinea pig SLC35F1 (83% identical), tropical clawed frog slc35f1 (79% identical), zebrafish slc35f1 (78% identical), Caenorhabditis elegans Y73E7A.3 (38% identical). Paralogues in human: SLC35F2 (51% identical).
Diseases named in the same sentence as SLC35F1 in open-access papers:
SLC35F1 is named in the same sentence as 17 diseases in open-access papers, as found by Europe PMC text mining. Sharing a sentence is not in itself a finding about the gene and the disease. The quoted sentences say what the papers report.
atrial fibrillation (2 papers, 2021 to 2023). A disorder characterized by an electrocardiographic finding of a supraventricular arrhythmia characterized by the replacement of consistent P waves by rapid oscillations or fibrillatory waves that vary in size, shape and timing and are accompanied by an irregular ventricular response. "The loci we associated with coronary artery disease (FOXC1), myocardial infarction (USP39), and atrial fibrillation (SLC35F1 and SSPN) through their effects on RHR have been associated with these cardiovascular diseases in recent studies." (PMID 37532724, 2023). "Atria-Enriched GJA5, KCNA5 and NPPA, RA-Enriched HCM4, MIR100HG, REC114 and SMAD7 and Ventricles-Enriched KCNJ2, MYH7, PHLDB2, RPL2L and SLC35F1 were associated with atrial fibrillation." (PMID 34088950, 2021).
Rett syndrome (2 papers, 2023 to 2025). A severe neurodevelopmental disorder affecting the central nervous system. "In addition, it has recently been described that a patient carrying a mutation in the SLC35F1 gene exhibited a Rett syndrome-like phenotype (RTT): The patient, among others, experienced seizures and was unable to walk independently." (PMID 36951990, 2023). "Moreover, since SLC35F1 deficiency can lead to a phenotype that resembles Rett syndrome, we analyzed the Slc35f1 mice in the marble-burying test." (PMID 36951990, 2023). "It was found that SNHG5 was involved in neurological disorders, SLC35F1 was involved in neurological disorders, developmental and epileptic encephalopathies resembling Rett syndrome." (PMID 40384935, 2025).
Stroke (1 paper, 2015). Sudden impairment of blood flow to a part of the brain due to occlusion or rupture of an artery to the brain. "In Chr 6q21–22, SNPs near AIM1–ATG5 are associated with stroke (P = 9.2 × 10-6) and plasma VLDL concentration (P = 4.7× 10-7), those near DCBLD1 are associated with carotid artery disease (P = 7.4 × 10-8), and a SNP in SLC35F1 is associated with heart rate (P = 4.0 × 10-10)." (PMID 25689165, 2015).
neurodevelopmental disorder (1 paper, 2023). A behavioral and cognitive disorder with onset during the developmental period that involves impaired or aberrant development of intellectual, motor, or social functions. "Malfunction of SLC35F1 in humans is associated with neurodevelopmental disorders." (PMID 36951990, 2023).
psychiatric disease (1 paper, 2025). "Our results also showed that many psychiatric disease-associated remarkable genes, were upregulated (SLC35F1, SNHG5, and FAM118A) or downregulated (SLC26A3, SLC27A4, LINGO1, and RASGEF1B) in PBMCs of patients with WD." (PMID 40384935, 2025).
SLC35F1 also shares sentences with these, for which no sentence is quoted: aneurysm (1 paper); Anxiety (1); cardiomyopathy (1); cardiovascular diseases (1); coronary artery disease (1); depression (1); epileptic encephalopathies (1); Intellectual disability (1); myocardial infarction (1); neurological disorders (1); psychological distress (1); tumour (1).